STK11 (serine/threonine kinase 11)
Diseases named in the same sentence as STK11 in open-access papers (continued):
Sharing a sentence is not in itself a finding about the gene and the disease.
cancer (continued). "Molecular aberrations that were shared in at least one P/X pair and that were previously recognized to have deleterious effects in human cancers included CHEK2 [K416E; 415S (SNP)], EGFR (158N), ATM (P1054R), STK11 (D194N), PIK3CA (E545K), KIT (798I; M541L), and RUNX1 (L56S)." (PMID 34714554, 2022). "The STK11 gene is located on the short arm of chromosome 19 (19p13.3) and its nine exons codes for liver kinase B1 (LKB1), a protein kinase and master metabolic sensor that acts as an energy gauge to sustain cancer cell survival." (PMID 33572782, 2021). "Our screen for differentially expressed genes also identified Stk11 (also known as Lkb1) a kinase well studied in the contexts of cancer, cell growth and development, but not previously studied in the contexts of learning and neuronal plasticity." (PMID 32779566, 2020). "This last finding was confirmed by a different group which reported a prevalence of KEAP1-NFE2L2 (31%) alterations in tumors with high neuroendocrine gene expression, mainly co-occurring with STK11 and KRAS genes to exert a synergic role of tumorigenesis enhancement and cancer progression." (PMID 31126053, 2019). "To investigate whether the HMA-resistance-specific CNAs influence gene expression, we assayed the expression of 8 cancer-related genes by quantitative reverse transcription PCR (RT-qPCR) including BCL9, ARNT, ABL2, STK11, TCF3, SMARCA4, RUNX1, and U2AF1." (PMID 28052028, 2017). "Here, we report a novel mutation of STK11 in a PJS patient without a family history, which is associated with definite cancer risk." (PMID 29141581, 2017). "These segments contain known cancer genes including MYC, EGFR, ERBB2 CDKN2A, RB1 and STK11." (PMID 28686671, 2017). "In the responsive group, 9 mutations (26%) were found in genes concerning proliferation pathways: PIK3CA (2 ADC with exon 9 E545K, and a poorly differentiated carcinoma with H1047R), BRAF (V600E in 2 ADC), STK11 (V197fs 69 in one ADC and F354L in one SCC), NTRK2 (L755L in a SCC) and MET (N375S)." (PMID 25561229, 2014). "Studies that have formally estimated cancer risks in PJS have not computed separate estimates according to LKB1/STK11 status." (PMID 12865922, 2003). "PJS with germline mutations in LKB1/STK11 are at a very high relative and absolute risk of multiple gastrointestinal and nongastrointestinal cancers." (PMID 12865922, 2003). "Given the previously noted reduction in macrophage-related gene expression in KEAP1 and/or STK11 mutant patient tumors, these findings suggest that Kynu expression in GEMMs is primarily driven by macrophage infiltration rather than cancer cell-intrinsic expression." (PMID 40427178, 2025). "Similarly, immune-activating chemokine receptor genes tended to show a negative correlation with PEBP1/STK11 co-expression across all cancer types examined." (PMID 40806276, 2025). "Using real-world data, we assessed the effect of KRAS G12C mutation with or without STK11 and/or KEAP1 mutations on overall survival (OS) in patients with aNSCLC receiving cancer immunotherapy (CIT), chemotherapy, or both in first line (1L) and second line (2L)." (PMID 37069542, 2023).
cancer (continued). "Since STK11 and AMPK have been shown to be involved in the maintenance of redox homeostasis and reactive oxygen species (ROS)-induced cancer cell death, the functioning of the STK11-AMPK pathway may be a negative predictor of response to ROS-induced therapies." (PMID 35163487, 2022). "Finally, CNAtra successfully detected the previously-reported focal amplifications of MYC (NCI-H82) and MYCN (CHP-212, IMR-32) loci as well as homozygous focal deletions of BANK1/4q24 (NCI-H82), LKB1/STK11 (A427), and p16INK4a/CDKN2A (A427) loci in respective cancer cell lines." (PMID 32299346, 2020). "The top 15 SGA-FIs connected with CSMD3 and ZFHX4 also form densely connected networks that include well-known cancer drivers, such as KRAS, GATA3, KEAP1, ERBB2 and STK11, suggesting that alteration of CSMD3 and ZFHX4 may perturb some of the same signaling pathways as do these known drivers." (PMID 31276486, 2019). "ECM proteases generally showed a widespread negative correlation with PEBP1/STK11 co-expression across all cancer types, with the exception of MMP15 and SPG7, which displayed positive correlations in most of the cancers analyzed." (PMID 40806276, 2025). "Our results revealed both positive and inverse correlations between PEBP1/STK11 co-expression and TME-related molecular signatures, which did not align with classical cancer categorizations." (PMID 40806276, 2025). "More specifically, HK3 displayed predominantly negative correlations across most cancer types, suggesting a widespread involvement of these enzymes in metabolic pathways influenced by PEBP1/STK11 levels." (PMID 40806276, 2025). "Among other genes that encode immune inhibitors, IL10, TGFBR1, and IDO1 exhibited a broadly negative correlation across most cancer types, aligning with the expression pattern of PEBP1/STK11." (PMID 40806276, 2025). "Nevertheless, in several cancers, hypoxia-related molecules generally showed a negative correlation with the co-expression of PEBP1/STK11, including CHOL, LIHC, PAAD, BLCA, BRCA, UCS, LUAD, and SARC." (PMID 40806276, 2025). "Here we report the analysis of the LKB1/STK11 locus in a series of 33 PJS families, and estimation of cancer risks in carriers and noncarriers." (PMID 12865922, 2003).
adenocarcinoma (72 papers, 1999 to 2026). A common cancer characterized by the presence of malignant glandular cells. "We identified a higher rate of mutations and deletions (23%) in the STK11 tumor suppressor gene in adenocarcinomas versus SCC." (PMID 41742943, 2026). "All three patients with SD had NSCLC, two of whom had low PD-L1 expression (1-49%), STK11 wildtype but KRAS-mutated adenocarcinoma, and were previously treated with an immune checkpoint inhibitor." (PMID 41523436, 2025). "STK11 alterations in KRAS-driven NSCLC adenocarcinomas are associated with low PD-L1 (Programmed Death-Ligand 1) levels, leading to reduced efficacy of anti-PD-1 monoclonal antibody therapy." (PMID 39011112, 2024). "Recent studies have highlighted the substantial impact of STK11 mutations in the highly prevalent KRAS-driven NSCLC adenocarcinomas, presenting distinct biological characteristics, therapeutic susceptibilities, and immune profiles." (PMID 39011112, 2024). "Researchers previously reported that Cre-induced knockout of both LKB1 (mouse gene Stk11) alleles in the endometrium of mice (Sprr2f-Cre; Lkb1L/L) promotes the development of highly invasive adenocarcinomas in 100% of mice." (PMID 35565271, 2022). "Analysis for these gain-of-function mutations in KRAS showed concomitant KRAS mutations with loss of STK11 in adenocarcinoma." (PMID 33652656, 2021). "Regarding lung LCNEC, the adenocarcinoma-like subtype defined by the presence of KRAS or STK11 mutations have higher response rates to the pemetrexed/platinum chemotherapy doublet." (PMID 33562726, 2021). "Mutation analysis for STK11 and PTEN shows a differential preference with loss of STK11 predominately seen in adenocarcinoma and loss of PTEN in SCC." (PMID 33652656, 2021). "Data in relevant mouse models of KRAS mutant/STK11 deficient adenocarcinoma fully supported this hypothesis." (PMID 40069402, 2025). "Notably, STK11 variants are frequently observed in non-small cell lung cancer (NSCLC) adenocarcinomas and are associated with poor survival." (PMID 39011112, 2024). "Inactivating LKB1/STK11 germline mutations in combination with loss of the wild-type allele by chromosomal loss or methylation are responsible for the development of hamartomatous polyps and adenocarcinomas in Peutz–Jeghers syndrome patients." (PMID 15138480, 2004). "CL7 included only combined adenocarcinomas, most of which harbored mutations in KRAS and/or KEAP1 and STK11." (PMID 40144596, 2025). "KRAS, BRAF, STK11/KEAP1, MUTYH/RET, and RBM10/MET-associated modules showed the opposite trend, having significantly higher frequencies of adenocarcinoma cases as genomic alterations increased (P ≤ 0.02)." (PMID 39664186, 2024). "KRAS mutations are found in 30% of NSCLC adenocarcinomas, while patients with KRAS mutations are KRAS/STK11 co-mutated 15–32% of the time in the metastatic setting." (PMID 37373999, 2023). "The adenocarcinoma I1 and carcinoid I2 components of the mixed neoplasm shared the same mutations in BRAF (p.Gly466Ala), NF1 (p.Pro1359LeufsTer19 and p.Glu1928Ter), STK11 (p.Gly188AlafsTer99), and AKT2 (p.Leu52Ter) genes." (PMID 34926584, 2021).
adenocarcinoma (continued). "Liver kinase B1 (LKB1, also known as Serine/threonine kinase 11, STK11), responsible for maintenance of the balance between anabolic and catabolic processes, is mutated in about 30% of all adenocarcinoma and the co-mutation with KRAS is often reported." (PMID 38163906, 2024). "Somatic STK11 disruption is common in KRAS-driven LUADs (~10–15%), but rare in other KRAS-driven adenocarcinomas (pancreatic ~1.5%, colorectal ~1.2%)." (PMID 37968341, 2024). "Significant differences can be found in the mutation rate of EGFR (60.9% vs 11.9%), KRAS (12.2% vs 25.0%), STK11 (1.5% vs 11.9%), FGFR3 (2.4% vs 0.0%) and ERBB4 (1.2% vs 6.1%) between adenocarcinoma in our cohort and TCGA-LUAD data (all p < 0.001)." (PMID 38496837, 2024). "The three most frequently altered genes in a subgroup of smokers with adenocarcinoma were EGFR (22.0%), STK11 (19.0%), and KRAS (12.0%)." (PMID 22768234, 2012). "In a subgroup of non-smokers with adenocarcinoma, EGFR was the most frequently altered gene, with a mutation rate of 49.8%, followed by EML4-ALK (9.3%), PTEN (9.1%), PIK3CA (5.2%), c-Met (4.8%), KRAS (4.5%), STK11 (2.7%), and BRAF (1.9%)." (PMID 22768234, 2012). "However, STK11 alterations are virtually non-existent in adnexal mullerian adenocarcinomas." (PMID 38376618, 2024). "The third NSCLC patient with SD was immune checkpoint inhibitor-naïve, had PD-L1 negative adenocarcinoma, and no KRAS/STK11/KEAP1 alteration was seen." (PMID 41523436, 2025).
infection (24 papers, 2010 to 2025). The state of being infected such as from the introduction of a foreign agent such as serum, vaccine, antigenic substance or organism. "Naïve Huh7 cells inoculated with cell- culture-produced infectious HEV particles did not affect the expression of AMPKα or its upstream regulatory kinase genes CAMKK1, CAMKK2 and STK11 at the transcriptional level at 24 h post-infection." (PMID 40074929, 2025). "To this end, we infected Stk11-ΔM and control mice with Spneu 6303 and measured bacterial growth and dissemination, and lung inflammatory reactions at 12 and 40 h after infection." (PMID 36096803, 2022). "Here we demonstrated that the integrity of intestinal-epithelium barrier and function are damaged with a greater extent in Atg7-/-;Stk11-/- mice compared with Stk11-/- mice, leaving the mice vulnerable to infection." (PMID 33236987, 2020). "Specifically, infection of Shh-Stk11 tracheal rudiments with the Ad-MARK3CA virus significantly increased the percentage of ciliated cells as compared to Shh-Stk11 tracheal rudiments infected with the Ad-GFP or Ad-MARK3WT viruses." (PMID 31636950, 2019). "Infection of Shh-Stk11 tracheal rudiments with the Ad-MARK3CA virus led to a significant reduction in the proportion of Ki67+ epithelial cells compared to tracheal rudiments infected with either the Ad-GFP or Ad-MARK3WT virus." (PMID 31636950, 2019). "No significant change of proliferation was observed on Shh-Stk11 tracheal rudiments with either Ad-GFP or Ad-STK11KD infection." (PMID 31636950, 2019). "We found that broad-spectrum antibiotics supplementation could partially rescue the death of Atg7-/-;Stk11-/- mice, but not Stk11-/- mice, suggesting the role of autophagy in preventing infection-related death." (PMID 33236987, 2020).
metabolic disorders (21 papers, 2014 to 2026). "Loss of function or mutation of STK11 may cause metabolic disorders and stress responses of renal tubular cells, contributing to the development of CKD." (PMID 40289841, 2025). "Unlike tissue-specific Stk11 knockout alone, systemic Lkb1 ablation in adult mice may cause severe host metabolic disorders due to multiple organ failure, which may not be observed by histology H&E staining alone." (PMID 33236987, 2020).
autosomal dominant disease (14 papers, 2014 to 2025). Autosomal dominant form of disease. "Peutz–Jeghers syndrome is a rare autosomal dominant disease caused by germ line mutations in STK11/LKB1." (PMID 34069790, 2021). "Peutz–Jeghers syndrome (PJS) is a Mendelian autosomal dominant disease caused by mutations in the tumor suppressor gene, serine/threonine kinase 11 (STK11)." (PMID 29245219, 2017). "Mutations in STK11, the gene encoding human LKB1 (hLKB1) are the cause of the Peutz–Jeghers Syndrome (PJS), a rare autosomal dominant disease, which manifests in intestinal benign polyps and mucocutaneous mispigmentations/lentigines." (PMID 36899949, 2023). "The substitutions of single amino acids in highly conserved regions of the STK11 protein are associated with Peutz–Jeghers syndrome (PJS), which is an autosomal dominant inherited disorder." (PMID 31712642, 2019). "PJS is a rare autosomal dominant inherited disorder caused by a germline PV in the STK11 gene, also known as the LKB1, which is located on 19p13.3 and comprises nine coding exons and one noncoding exon, coding a member of the serine/threonine kinase family with 433 amino acids." (PMID 35163487, 2022).
lung (12 papers, 2015 to 2024). "In addition, loss of chromosomal segments containing STK11 was detected in 10% of AAH, 20% of AIS, 35.7% of MIA and 38.5% of ADC lesions (p = 0.02558, χ2 test for trend in proportions), implying STK11 loss may be a later genomic event during initiation or progression of lung preneoplasia." (PMID 31278276, 2019).
genetic disorders (4 papers, 2014 to 2025).
bacterial infection (3 papers, 2018 to 2025). "However, the cause of Stk11-/- mice death could be systemic catastrophe, rather than bacterial infection alone based on serum metabolomics profiling with the depletion of amino acids, essential metabolites and low glucose." (PMID 33236987, 2020).
STK11 also shares sentences with these, for which no sentence is quoted: Insulin resistance (24 papers); Hyperglycemia (21); glioma (20); Familial adenomatous polyposis (12); Li-Fraumeni syndrome (12); liver cancer (10); osteosarcoma (10); Glucose intolerance (9); liver fibrosis (9); acute myeloid leukemia (8); adenosquamous carcinoma (8); atherosclerosis (7); familial atypical multiple mole melanoma syndrome (7); adenoma (6); esophageal cancer (6); head and neck squamous cell carcinoma (6); Hereditary Non-Polyposis Colorectal Cancer (6); large cell carcinoma (6); neuroblastoma (6); non-alcoholic fatty liver disease (6); cardiomyopathy (5); diabetic nephropathy (5); endothelial dysfunction (5); gastrointestinal neoplasms (5); glioblastoma (5); prostate tumors (5); skin cancer (5); asthma (4); autoimmune disease (4); benign tumors (4).
A further 275 diseases each share a sentence with STK11 in 4 papers or fewer.